DSG2 (desmoglein 2)
Diseases named in the same sentence as DSG2 in open-access papers (continued):
Sharing a sentence is not in itself a finding about the gene and the disease.
tumor (continued). "This suggests that Dsg2-Hh crosstalk can enhance tumor promotion, but that it is most likely dispensable for Dsg2-mediated cutaneous tumor development and progression." (PMID 25871385, 2015). "Specifically, the expression of DSG2 was generally high in well differentiated areas of the tumor (low Gleason Score) and low in poorly differentiated areas of the tumor (high Gleason Score)." (PMID 24896103, 2014). "JO-1 binding to DSG2 on tumor cells triggers pathways involved in EMT, a process which has been associated with tumor metastasis." (PMID 23898462, 2013). "DSG2-targeting Ad3 based vectors therefore efficiently transduce tumor cells after intravenous injection into mice." (PMID 24204268, 2013). "Therefore, our findings emphasise that DSG2 plays a crucial role in tumour growth and stemness both in vitro and in vivo." (PMID 40615400, 2025). "DSG2 is a member of the desmosomal cadherin family, which may play a role in tumour–stroma crosstalk." (PMID 40615400, 2025). "The study found that overexpression of DSG2 significantly promoted tumour growth." (PMID 40615400, 2025). "Interestingly, unlike these studies, our observations showed that CTC cluster DSG2 expression was significantly elevated, and E-cadherin was significantly decreased compared to adherent cells representing primary tumor tissues." (PMID 41381723, 2025). "Besides, overexpression of TROP2 decreases the expression level of desmoglein 2 (DSG2), activates EGFR-AKT and DSG2-plakoglobin(PG)-β-catenin pathways to promote tumor cell invasion and migration." (PMID 40936682, 2025). "However, other studies have shown that the downregulation of the adhesion junction component E-cadherin and the desmosome components DSG2 and DSC2 is associated with increased tumor metastasis and poor prognosis." (PMID 41381723, 2025). "Thus, we suggested that hirudin inhibits CTC clustering is not merely through suppressing cell adhesion, but more critically by blocking the DSG2-mediated strengthening of desmosome junctions within tumor cells." (PMID 41381723, 2025). "High expression of DSG2 increased tumour resistance to osimertinib in lung cancer." (PMID 40615400, 2025). "Analysis of data from the TCGA revealed that DSG2 was upregulated in 25 of 34 tumour types." (PMID 40615400, 2025). "Furthermore, cell–cell interaction analysis revealed that the DSC2 gene interacts with the DSG2 gene within tumor cells, and pathway analysis verified the upregulation of the DSC2–DSG2 protein complex structure specifically in TNBC." (PMID 38539508, 2024). "Here, DSG2 KO cells led to lower metastatic tumor cell burden." (PMID 39107343, 2024). "Thus, DSG2 would potentially inhibit metastasis at this early step of the metastatic cascade by preventing invasion and dissociation from the primary tumor." (PMID 39107343, 2024). "Current literature suggests that DSG2 plays a broad and significant role in regulating various cancer cell functions, including cell proliferation, survival, migration, invasion, adhesion, cell cycle progression, vesicle secretion, and tumor development." (PMID 38188287, 2023). "The direct impact of these factors modulated by DSG2 requires further study, but early studies show that exosomes derived from DSG2 overexpressing cancer cells enhance dermal fibroblast cell growth, demonstrating that DSG2 expression can modulate the tumor microenvironment." (PMID 38188287, 2023). "DSG2 critically influences cell adhesion, epithelial cell proliferation, and tumor formation." (PMID 37372393, 2023). "Furthermore, A431-Dsg2/GFP xenografts in immunocompromised mice resulted in significantly greater tumor growth and higher plasma sEV levels, and a single dose of 20 μg Dsg2 modulated sEVs was able to enhance the tumorigenic potential of A431-GFP xenografts." (PMID 36291882, 2022). "We developed a syngeneic tumor cell line (TC1-DSG2) that expressed human DSG2 at a high level." (PMID 36360292, 2022).
tumor (continued). "Together with the pooled OS and OR of the indicated clinicopathological features, our analyses suggested DSG2 may function as a promoter of tumor progression, which is supported by our mining of the TCGA database." (PMID 35345582, 2022). "Dsg2 is involved in tumor progression through the regulation of EGFR and Src kinase activity." (PMID 32989241, 2021). "A previously published study reported that a higher mRNA expression level of DSG2 predicted a significantly poorer prognosis in TCGA-PAAD, whereas DSG2 protein expression in PC tumor tissues detected by immunohistochemical staining in the in-house cohort showed no significant prognostic value." (PMID 34993253, 2021). "Although the role of desmosomes in carcinogenesis is relatively unknown, several lines of evidence have shown that desmoglein-2 (Dsg2) can function either as a tumor suppressor or an oncogene in a context-dependent manner." (PMID 32989241, 2021). "The expression of DSG2 is related to the tumor size, lymph node metastasis and TNM stage." (PMID 32095325, 2020). "The emphasized doxorubicin resistance of SKOV-3 and SKOV-3.ip cells cultured in collagen hydrogel confirms the hypothesis that the reduction in desmoglein-2 level contributes in tumor aggressiveness due to a shift towards mesenchymal morphology." (PMID 33291824, 2020). "Shedding of DSG-2 breaks cell–cell contacts and promotes viral spread, but might also promote easier spread of tumor cells and thereby metastasis." (PMID 32957644, 2020). "Although the role of desmosomes in carcinogenesis is still unknown, previous studies have shown that Dsg-2 can act either as a tumor suppressor or an oncogene." (PMID 33372636, 2020). "DSG-2 expression was also associated with the tumor size in non-small cell lung cancer, and lung adenocarcinoma." (PMID 32957644, 2020). "In the interfollicular epidermis, DSG1 and DSG2 are normally expressed at very low level and restricted to the proliferative basal cell layer, leading to tumour cells with high DSG1 or DSG2 expression that often exhibit high malignancy, which is identified by all previous research." (PMID 32850288, 2020). "Reduction in the abundance of representative proteins of tight junctions (occludin and ZO-1), gap junctions (connexin-43) and desmosomes (desmoglein-2) was established in 3D tumor models compared to monolayer, with the most pronounced suppression in collagen hydrogel." (PMID 33291824, 2020). "However, some studies have shown that DSG2 is expressed at lower levels in cancer and functions as a tumor suppressor." (PMID 32514251, 2020). "Interestingly, DSG2 RNA expression levels in the tumor tissue from the 12 patients were significantly negatively correlated with the fold change in the peak number of CD8+ TILs at 1 or 2 months (Spearman's rank correlation, R = −.6270; P = .03)." (PMID 31944306, 2020). "However, some studies showed that the downregulation of DSG2 promoted the proliferation and metastasis of cancer cells because desmosome downregulation decreases adhesion junctions to drive tumor development and early invasion." (PMID 32514251, 2020). "We have developed small, recombinant proteins which bind a critical junction protein, desmoglein 2, triggering the transient and specific opening of tumor tight junctions allowing for infiltration of the tumor with immune cells, oncolytic viruses, drugs, and other therapeutics." (PMID 30992466, 2019). "The findings from these studies and the trials with ColoAd1 suggest that species B viruses that bind to CD46 and/or desmoglein 2, both highly expressed on most tumour types, may have a potential advantage in future developments of oncolytic viruses." (PMID 29904022, 2018). "However, one patient had a DSG2− primary tumor and a DSG2+ metastasis and a second patient had a DSG2+ primary and a DSG2− metastasis." (PMID 27340778, 2016).
tumor (continued). "Furthermore, other members of the desmosomal cadherin family were expressed at low level in a small number of TCGA tumors, and DSG1, DSC2 and DSC3 were all significantly enriched in the DSG2-high tumor subset." (PMID 27340778, 2016). "Taken together, the data obtained here suggest that Dsg2 may play a significant role in tumor development by positively regulating EGFR level and signaling through a c-Src and Cav1 dependent manner." (PMID 26918609, 2016). "In cancerous tissues, 7/13 tumour specimens (54 %) contained DSG2+ vessels (Online resources Supp." (PMID 27338829, 2016). "Moreover, our data specifically suggests that two distinct mechanisms of Dsg2-Hh synergy are responsible for the effects on the different tumor types." (PMID 25871385, 2015). "Therefore, we crossed these two mouse models to determine if Dsg2 and Hh interact during chemical-induced tumor development." (PMID 25871385, 2015). "Additionally, DMBA/TPA induced BCC formation in all mice harboring the Ptc1+/lacZ gene and the presence of Dsg2 in Dsg2/Ptc1+/lacZ mice doubled the BCC tumor burden." (PMID 25871385, 2015). "Thus, the Inv-Dsg2/Ptc1+/lacZ mice have accelerated macroscopic tumor formation compared to all other genotypes." (PMID 25871385, 2015). "Importantly, the BCC tumor burden was ~2 fold larger in Inv-Dsg2/Ptc1+/lacZ compound animals compared to Ptc1+/lacZ mice, suggesting that the presence of Dsg2 enhances BCC development in the Ptc1 heterozygote background." (PMID 25871385, 2015). "It is therefore possible that activation of the Hh pathway in the dermis in a Shh-dependent manner could account for the earlier tumor emergence in the Inv-Dsg2/Ptc1+/lacZ mice." (PMID 25871385, 2015). "In particular, Ptc1 is an inducer of apoptosis, and inhibition of its function by Dsg2 could increase cell survival and tumor formation." (PMID 25871385, 2015). "Interestingly, after week 13 the difference in tumor number between Inv-Dsg2 and Inv-Dsg2/Ptc1+/lacZ mice leveled off." (PMID 25871385, 2015). "Interestingly, in diffuse-type gastric cancers, decreased expression of Dsg2 is associated with poor prognosis suggesting a complex role for Dsg2 in oncogenesis, serving as a tumor enhancer or suppressor." (PMID 25785582, 2015). "However, the proper assessment of tumor targeting with these chimeras will require DSG2 or CD46 transgenic mice." (PMID 28548059, 2014). "We speculate that this is due to the fact that DSG2 in tissues, other than the tumor and a subset of epithelial cells in the intestine/colon, is not accessible to i.v. injected JO-1." (PMID 23898462, 2013). "Moreover, DSG2 expression resumes when tumor cells exit hypoxia conditions." (PMID 41381723, 2025). "However, the exact role of DSG2 in cancer remains unclear and appears to be complicated, with data indicating it can function as both a tumor suppressor and an oncogene in different cancer types." (PMID 35345582, 2022). "Altered expression of desmosome proteins may promote cancer development in certain contexts, but DSG2 affects carcinogenesis in different tumors in different ways, such as tumor composition, protein expression level, subcellular localization and tissue-specific proteins." (PMID 33407183, 2021). "Additionally, DSG-2 was shown to be involved in tumor vascular formation in melanoma." (PMID 32957644, 2020). "Thus, both DSG1 and DSG2 may inhibit tumour progression in EHCC, and function as prognostic biomarkers." (PMID 32850288, 2020). "Interestingly, E-ca as a tumor suppressor and DSG2 as a potential oncogene in CRC could be both increased by PNN overexpresion, which suggested the different mechanisms of PNN in CRC patients." (PMID 27107420, 2016).
tumor (continued). "Since compound Inv-Dsg2/Ptc1+/lacZ mice showed increased Hh signaling and hyperproliferation compared to Inv-Dsg2 animals, we investigated whether they are more susceptible to DMBA-TPA induced tumor development." (PMID 25871385, 2015). "Along the same line, anti-Dsg2 antibodies abrogated tumor xenograft growth and tumors of patients treated with ICI had lower Dsg2 levels." (PMID 39811728, 2024). "Dsg2-depleted GBC cells exhibited significantly enhanced proliferation, migration, and invasiveness in vitro and tumor growth and metastasis in vivo through Src-mediated signaling activation." (PMID 32989241, 2021). "The Ad11p virus offers several advantages within the context of improved delivery to tumours, including the use of CD46 and desmoglein-2 as primary receptors, rapid release from a cell, and lower seroprevalence." (PMID 30956777, 2019). "Consequently, the results of the IHC staining of xenograft tumours further confirmed that the number of macrophages, especially the number of CD68+ macrophages (M2), significantly decreased in the DSG2-knockdown group." (PMID 40615400, 2025). "Based on the previous experiments, DSG2-mediated binding of tumor cells to hepatocytes appears to be unlikely to contribute to the reduced retainment of DSG2 KO AsPC-1 in the liver." (PMID 39107343, 2024). "In SCC, Dsg2 promotes tumor development and progression by increasing the production of ICAM-1 and IL-8, which inhibit leukocyte binding and promote inflammation and, ultimately, tumor progression." (PMID 37173918, 2023). "To date, there is no distinguishing feature that identifies the ‘tumor promoting’ from the ‘tumor suppressing’ role of DSG2 in cancer." (PMID 38188287, 2023). "Adenoviral vectors such as HAdV-C5 and HAdV-B3 which use CAR and DSG2, respectively, could be utilised to target GBM via local delivery into the tumour." (PMID 37243172, 2023). "DSG2-mediated Ad5/3-luc(L) transduction of other epithelial tissues was 1–2 orders of magnitude lower than tumor-transduction, likely because DSG2 is not readily accessible in normal epithelial tissues." (PMID 36360292, 2022). "The study showed that DSG2 and DSC2 play opposite roles in tumor proliferation." (PMID 33407183, 2021). "The low expression of DSG2 in HNC is in line with the result of its functional study, in which DSG2 may act as a tumor suppressor to enhance intercellular adhesion." (PMID 34203070, 2021). "The acidosis-related signature is composed of seven key genes (ARNTL2, DKK1, CEP55, CTSV, MYEOV, DSG2, and GBP2), all of which have elevated expression levels in PC tumor tissues compared with normal tissues and are all related to adverse clinical outcomes in patients with PC." (PMID 34993253, 2021). "The DSG2 RNA expression levels in the tumor tissue from the 12 patients positively correlated, but not significantly with the number of viral genomes in the patients' blood on day 4 (Spearman's rank correlation, R = .4526; P = .1401)." (PMID 31944306, 2020). "The protein expression of DSG1 and DSG2 was measured by EnVision immunohistochemistry in 15 normal biliary tract tissues, 10 biliary tract adenoma tissues, 30 peritumoral tissues, and 100 EHCC tumour tissues." (PMID 32850288, 2020). "Furthermore, overexpression of Dsg2 in the epidermis of transgenic mice enhances EGFR level and activates mitogenic signaling leading to epidermal hyperplasia and sensitivity to tumor development." (PMID 26918609, 2016). "Furthermore, Dsg2 upregulates Hedgehog signaling and in response to chemical carcinogens, enhances BCC and SCC tumor development." (PMID 26918609, 2016). "Overexpression of Dsg2 in the Ptc1 heterozygous background also leads to accelerated squamous tumor development in response to DMBA/TPA treatment; however, this effect is only observed during early tumor development." (PMID 25871385, 2015).
tumor (continued). "The DSG2 molecule is universally expressed on the surface of not only cancer cells, but also non-tumor tissue, and possibly on human astrocytes specifically when Ad5/35 and Ad5/11 application is decreased." (PMID 25738357, 2015). "Lack of difference in overall tumor burden but evidence of decreased tumor latency in response to chemical carcinogens in Inv-Dsg2/Ptc1+/lacZ mice, suggests a possible synergistic effect of the two pathways on the rate of tumor promotion." (PMID 25871385, 2015). "We found that MCRS1 overexpression suppressed the expression of DSG2 mRNA, indicating that MCRS1 overexpression could impair cell adhesion and increase tumor invasion and metastasis." (PMID 25373388, 2014). "We identified several components of desmosomes – Dsp, Dsg2, desmocollin 2 (Dsc2; MGI: 103221), and plakophilin 2 (Pkp2; MGI: 1914701) – whose expression was significantly downregulated in the highly invasive tumor lesions that develop in the RT2 mouse model of PNET." (PMID 20862307, 2010). "The results revealed that the absence of DSG2 significantly inhibited tumour growth and relapse." (PMID 40615400, 2025). "Upregulation of DSG-2 might seem counterintuitive in cancer, as tumors need to break cell–cell contacts in order to metastasize, but signaling via DSG-2 might promote proliferation and migration of tumor cells." (PMID 32957644, 2020). "Additionally, DSG2 was significantly correlated with tumor size, PLNM, recurrence and vital status in 5 years, but not FIGO stage, pathologic type, differentiation grade, stromal invasion, LVSI, vaginal involvement and parametrial infiltration." (PMID 32514251, 2020). "However, depolarization of tumor cells during epithelial to mesenchymal transition (EMT) leads to localization of DSG2 protein throughout the tumor rather than only within the cell junctions." (PMID 30992466, 2019). "Tumor targeting results obtained in mice with chimeric Ad5 viruses containing Ad3 or Ad35 fibers also point in this direction because the Ad3 fiber binds to human DSG2 but not to mouse DSG2, and in mice the Ad35 fiber receptor CD46 is expressed only in testis." (PMID 28548059, 2014). "Furthermore, the changes in tumor cell clustering ability, adhesion strength and cell junction protein expression induced by HIF-1α knockdown could be significantly reversed by the addition of recombinant DSG2." (PMID 41381723, 2025). "In addition, negative expression of DSG1 and DSG2 was closely associated with several clinicopathological characteristics of EHCC, which could present aggressiveness and determine the malignant degree of the tumour." (PMID 32850288, 2020). "Lastly, we observed that all tumor samples from patients with CRC stained strongly with the group B adenovirus receptors CD46 and DSG2 (data not shown)." (PMID 28923104, 2017). "Remarkably, while performing the pathology analysis, we unexpectedly observed BCC tumor development in response to DMBA-TPA in Ptc1+/lacZ and Dsg2/Ptc1+/lacZ mice but not in WT or Inv-Dsg2 animals." (PMID 25871385, 2015). "Given the dual-targeting of JOC-x to DSG2 and poly(I:C) to TLR3, we predict our JOC-poly(I:C) may exhibit dose sparing qualities by resulting in less non-specific binding of poly(I:C) to non-tumor TLR3 cells as well as targeting the host-directed therapeutic to tumors." (PMID 30992466, 2019).